RASGRF1 (Ras protein specific guanine nucleotide releasing factor 1)
Diseases named in the same sentence as RASGRF1 in open-access papers (continued):
Sharing a sentence is not in itself a finding about the gene and the disease.
epilepsy (1 paper, 2017). A brain disorder characterized by episodes of abnormally increased neuronal discharge resulting in transient episodes of sensory or motor neurological dysfunction, or psychic dysfunction. "Therefore, we suggest that RASgrf1 is closely associated with epilepsy through the aberrant methylation of RASgrf1." (PMID 28611277, 2017). "Our data demonstrate that RASgrf1 is closely associated with epilepsy through aberrant methylation of RASgrf1 and that regulating the methylation status of relevant genes might be an intriguing topic for future research on epilepsy." (PMID 28611277, 2017). "We have previously observed the down-regulation of RASgrf1 in the temporal neocortex of epilepsy patients and in the hippocampus of epileptic animals." (PMID 28611277, 2017). "In spite of this, the fact that RG108 blocks epileptic seizure activity in response to KA treatment and changes the expression of RASgrf1 strongly supports the prediction that the methylation of some sites in the RASgrf1 promoter is involved in epilepsy." (PMID 28611277, 2017). "In addition, lower expression of RASgrf1 in the temporal neocortex of epilepsy patients and in the hippocampus of epilepsy animals has been reported in our previous study." (PMID 28611277, 2017). "However, due to its multifunctional nature, the exact mechanism of RASgrf1 in epilepsy still needs further research." (PMID 28611277, 2017). "Thus, we hypothesize that RASgrf1 expression and the hypermethylation of RASgrf1 might be related with epilepsy." (PMID 28611277, 2017).
epileptic seizures (1 paper, 2017). "We also found that, compared with the SE group, the RASgrf1 expression levels were slightly up-regulated on the 10th day and were significantly restored on the 45th day after acute epileptic seizures." (PMID 28611277, 2017).
Glucose intolerance (1 paper, 2014). Glucose intolerance (GI) can be defined as dysglycemia that comprises both prediabetes and diabetes. "Our analysis of the RasGrf1 KO mice showed significant reduction of pancreatic islet number and size, linked to diminished beta cell proliferation and neogenesis, and resulting in hypoinsulinemia, glucose intolerance and prediabetic state." (PMID 25421944, 2014).
heart failure (1 paper, 2018). Inability of the heart to pump blood at an adequate rate to meet tissue metabolic requirements. "The inhibition of RasGRF1 activity by drugs was effective in attenuating aging-induced cardiac fibrosis and heart failure." (PMID 30308936, 2018). "Therefore, this study investigated the role of RasGRF1 in heart failure induced by chronic diabetes." (PMID 30308936, 2018).
Hypoinsulinemia (1 paper, 2014). A decreased concentration of insulin in the blood. "RasGrf1 KO mice exhibit defects in memory consolidation, reduced body size, deficiency of IGF-1 and growth hormone, and hypoinsulinemia." (PMID 25421944, 2014).
insulinoma (1 paper, 2014). "Reporter luciferase assays in BT3 insulinoma cells demonstrated the ability of RasGrf1 to modulate mPttg1 promoter activity through ERK-mediated signals." (PMID 25421944, 2014). "In addition, reporter luciferase assays in transfected BTC3 insulinoma cells overexpressing RasGrf1 documented the ability of RasGrf1 to modulate Pttg1 promoter activity through ERK-dependent signals." (PMID 25421944, 2014).
intestinal tumors (1 paper, 2022). "In intestinal tumors, we observed regional hypomethylation of the Impact ICRs, whereas Rasgrf1 displayed regional hypermethylation (right)." (PMID 35873672, 2022).
mastitis (1 paper, 2010). Inflammation of breast tissue during lactation or postpartum due to an obstructed duct or infection. "It is unclear how RASGRF1 associates with resistance/susceptibility to mastitis; however, previous work has shown that expression of RASGRF1 affects the function of the growth hormone-insulin-like growth factor 1 (GH-IGF-1) axis, which can modulate the inflammatory response to mastitis." (PMID 20942903, 2010).
memory impairment (1 paper, 2023). "In conclusion, the present study showed that Rasgrf1 was regulated by miRNA-323-5p and that RasGRF1 downregulation may contribute to spatial learning and memory impairment after CCH." (PMID 37053022, 2023).
Myocardial fibrosis (1 paper, 2018). "The regulation of RasGRF1 attenuates myocardial fibrosis and improves cardiac function by inhibiting inflammation and oxidative stress in diabetic mice." (PMID 30308936, 2018).
non-small cell lung carcinoma (1 paper, 2023). A group of at least three distinct histological types of lung cancer, including non-small cell squamous cell carcinoma, adenocarcinoma, and large cell carcinoma. "This review describes the mechanisms of targeted-drug resistance and newly identified non-small cell lung cancer targets (e.g., KRAS G12C, NGRs, DDRs, CLIP1-LTK, PELP1, STK11/LKB1, NFE2L2/KEAP1, RICTOR, PTEN, RASGRF1, LINE-1, and SphK1)." (PMID 36909198, 2023).
pancreatic cancer (1 paper, 2021). "We can hypothesize that reduced expression of CACNA1H prevents Ca2+ influx for RASGRF1, which contributes to poor outcomes in patients with pancreatic cancer." (PMID 33431999, 2021).
psoriasis (1 paper, 2022). An autoimmune condition characterized by red, well-delineated plaques with silvery scales that are usually on the extensor surfaces and scalp. "Therefore, the difference found in RASGRF1 CNV between anti-TNF-induced PPP and non-induced psoriasis could be related to the fact that two of the patients developing induced psoriasiform reactions presented RA." (PMID 36143237, 2022).
reactive arthritis (1 paper, 2009). Reactive arthritis (ReA) is an autoimmune disorder belonging to the group of seronegative spondyloarthropathies and is characterized by the classic triad of arthritis, urethritis and conjunctivitis. "Here, we examine the potential relationship between RasGRF1 expression and MMP production in RA, reactive arthritis, and inflammatory osteoarthritis synovial tissue and FLS." (PMID 19678938, 2009).
tumor (15 papers, 2009 to 2025). "In addition to the common mutations, we observed some mutated genes appear specifically in primary tumour cell-enriched cell populations, such as those in AXIN3 and RASGRF1, were associated with tumour proliferation and invasion in previous studies." (PMID 34507604, 2021). "These clones harboured nonsynonymous mutations in genes that may be associated with tumour cell proliferation and invasion, such as RASGRF1 and RABGAP1L." (PMID 34507604, 2021). "Note repressed expression of RASGRF1 and DMBT1 was associated with increased tumor size, and high expression of FOSL1, FAM83A and MYEOV was associated with poor survival." (PMID 38245882, 2024). "Primary tumor cell populations were rich in AXIN3 and RASGRF1 genes mutation, known to be associated with tumor proliferation and invasion." (PMID 34833475, 2021). "RASGRF1/2 regulates Cdc42-mediated tumor cell transformation and cell motility, working as a tumor suppressor gene." (PMID 27993161, 2016). "We also evaluated expression of RasGRF1 in human primary ARMS tumor samples and noted pronounced upregulation of its expression at protein level as compared to normal skeletal muscle and surrounding tissue from normal patients (data not shown)." (PMID 22752028, 2012). "Consistent with the curve generated for the total population, RasGrf1−/− without tumors displayed a 20% increase in average lifespan as compared with tumor-free control mice (mean values WT: 99±4.5 weeks and RasGrf1−/−: 119±4.9; median WT: 102 weeks; RasGrf1−/−: 121 weeks) (p= 0.0003, Logrank test)." (PMID 21422498, 2011). "Notably, Cldn2, Fetub, Fst, Orm1, S100a14 and RasGRF1 were primarily detected in the cytoplasm of bronchial normal cells and tumor cells." (PMID 19812696, 2009). "In summary, we propose that the expression of HLA-DRB5 in malignant EP compartments and RASGRF1 in the TN_EP compartments may be associated with the occurrence of STAS and reveal the different tumor epithelial cell-enriched compartments’ characteristics of the NSTAS and STAS groups." (PMID 40786043, 2025). "Losing its self-inhibitory region of the RASGRF1 gene leads to continuously activated RAS-GTP and downstream signaling pathways, promoting cell transformation and tumor formation." (PMID 36909198, 2023). "Furthermore, knockdown of RasGRF1 in RMS cells inhibited ARMS cell growth in vitro and tumor formation in vivo in immunodeficient mice." (PMID 22752028, 2012). "Results from 454 sequencing confirmed activating Rasgrf1 insertions among the 29 Onc3 LUAA/LUAC tumors, including 10 large tumors from flash frozen genomic DNA which were also sequenced by SBCapSeq, and 19 additional smaller tumors isolated from FFPE tumor tissues." (PMID 33435458, 2021). "Finally, we employed SCID/beige mice to study tumor formation by RH30 wt and RH30 RasGRF1-kd cells." (PMID 22752028, 2012). "Compared with tumor nests in non-STAS patients, HLA-DRB5 and RASGRF1 were significantly less expressed in compartments of STAS, suggesting their inhibitory roles in the occurrence of STAS." (PMID 40786043, 2025).
cancer (11 papers, 2009 to 2025). A tumor composed of atypical neoplastic, often pleomorphic cells that invade other tissues. "Other tests are also useful in identifying cancer-causing targets, such as whole exome sequencing for RASGRF1 fusion and RICTOR amplification, whole-transcriptome sequencing for CLIP1-LTK fusion, and RNA sequencing for LINE-1-FGGY." (PMID 36909198, 2023). "In the Cancer Genome Atlas (TCGA) test dataset, eight genes were detected, and six of them were survival associated (DPP4, FFAR4, RASA3, RASGRF1, XCR1, and STX11)." (PMID 34760708, 2021). "As RasGRF1 expression levels regulate MMP production in cancer cell lines, we examined whether modulation of RasGRF1 expression in RA FLS might also regulate constitutive MMP and cytokine production." (PMID 19678938, 2009). "In the case of Fst and RasGRF1 strong cytoplasmic and nuclear staining was observed, where as the expression of Cldn2 was restricted to the cytoplasm and patchy throughout neighboring cancer cells." (PMID 19812696, 2009). "One plausible explanation for these longevity promoting effects could be the role of RASGRF1 in RAS activation and hence, in cancer development." (PMID 21422498, 2011).
adenocarcinoma (2 papers, 2009 to 2025). A common cancer characterized by the presence of malignant glandular cells. "Unlike the down-regulated GEFs, we found RasGRF1 (RAS protein-specific guanine nucleotide-releasing factor 1) 11.3-fold up-regulated in adenocarcinoma as compared with transgenic and 25.4-fold in the comparison adenocarcinoma vs non-transgenic." (PMID 19812696, 2009).
brain disorder (1 paper, 2021). A disease affecting the brain or part of the brain. "Finally, residue scanning, MD simulations, and MM-GBSA calculations were used to identify 18 most promising α-helix-shaped peptides that will be assayed to check their potential activity against Ras-RasGRF1 and prevent downstream molecular events implicated in brain disorders." (PMID 34832880, 2021).
RASGRF1 also shares sentences with these, for which no sentence is quoted: acute myeloid leukemia (2 papers); Dyskinesia (2); melanocytic neoplasm (2); pancreatic ductal adenocarcinoma (2); sarcoma (2); adrenocortical tumors (1); alveolar rhabdomyosarcoma (1); autoimmune disease (1); Beckwith-Wiedemann syndrome (1); Cerebral ischemia (1); cholangiocarcinoma (1); chronic kidney failure (1); fibrosis (1); glioma (1); infection (1); large cell neuroendocrine carcinoma of the lung (1); leukemia (1); liver cancer (1); lung carcinoma (1); neuroblastoma (1); Obesity (1); refractive error (1); sleep disorder (1); squamous cell carcinoma (1); transient neonatal diabetes mellitus (1).